ZEB1-AS1 (ZEB1 antisense RNA 1)
Gene: Long non-coding RNA gene on chromosome 10 (31,204,982 to 31,320,484, reverse strand). Ensembl gene ENSG00000237036.
Diseases named in the same sentence as ZEB1-AS1 in open-access papers:
ZEB1-AS1 is named in the same sentence as 7 diseases in open-access papers, as found by Europe PMC text mining. Sharing a sentence is not in itself a finding about the gene and the disease. The quoted sentences say what the papers report.
colorectal cancer (2 papers, 2020 to 2022). A primary or metastatic malignant neoplasm that affects the colon or rectum. "ZEB1AS1 is a famous cancer-related lncRNA, and its overexpression is widely found in various cancers, including colorectal cancer." (PMID 36203430, 2022).
glioma (1 paper, 2020). A benign or malignant brain and spinal cord tumor that arises from glial cells (astrocytes, oligodendrocytes, ependymal cells). "ZEB1 antisense RNA 1 (ZEB1-AS1) was shown to be highly expressed in glioma tissues, and to be closely related to glioma clinical stage, which suggested its involvement in glioma progression." (PMID 32650527, 2020).
melanoma (1 paper, 2019). A malignant, usually aggressive tumor composed of atypical, neoplastic melanocytes. "Also, we observed upregulation of the lncRNA ZEB1-AS1 (ZEB1 antisense RNA 1) in melanoma cell lines." (PMID 31383874, 2019).
ZEB1-AS1 also shares sentences with these, for which no sentence is quoted: cancer (2 papers); lung carcinoma (1); osteosarcoma (1); tumour (1).